RNU6-816P (RNA, U6 small nuclear 816, pseudogene)
Gene: Small nuclear RNA gene on chromosome 22 (15,701,459 to 15,701,565, forward strand). Ensembl gene ENSG00000212216.
Homologues: Orthologues: chimpanzee U6 (97% identical), chimpanzee U6 (96% identical), macaque U6 (95% identical), chimpanzee U6 (94% identical), macaque U6 (93% identical), guinea pig U6 (77% identical), dog U6 (76% identical), pig U6 (65% identical). Paralogues in human: RNU6-1239P (100% identical), RNU6-1268P (100% identical), RNU6-473P (98% identical), RNU6-617P (98% identical), RNU6-848P (98% identical), RNU6-1049P (97% identical), RNU6-127P (97% identical), RNU6-1021P (93% identical), RNU6-286P (93% identical), RNU6-631P (93% identical), RNU6-749P (93% identical), U6 (93% identical), and 1286 more.